SOD1 (superoxide dismutase 1)
Diseases named in the same sentence as SOD1 in open-access papers (continued):
Sharing a sentence is not in itself a finding about the gene and the disease.
neuroblastoma (continued). "Induced neuroblastoma LHI furthermore consisted of 15–25 nm granule-coated fibrils, a hallmark of mutant SOD1-linked FALS, raising the possibility that these acutely induced aggregations represent a precursor to LBHI/Ast-HI seen in advanced FALS." (PMID 17925878, 2007). "A significantly higher density of living cells after pneumolysin treatment was observed in cultures of Wt-SOD1 cells compared to G93A-SOD1 neuroblastoma cultures." (PMID 17997855, 2007). "The anti-oxidant N-acetylcysteine has been shown to restore mitochondrial function and to lower the production of reactive oxygen species in neuroblastoma cells expressing mutant SOD1." (PMID 17997855, 2007). "Exposure to 1 and 3 μg/ml tunicamycin (21.1% and 17.5%, respectively) or 0.3 and 1 μM thapsigargin (27.0% and 27.2%, respectively) significantly increased the number of cells containing SOD1 aggregates, in L84V SOD1 expressing neuroblastoma cells." (PMID 17925878, 2007). "In previous studies, we showed that the constitutive SOD-1 secretion in SK-N-BE human neuroblastoma cell line might be inhibited by Brefeldin A, that impairs the classical ERGP, as well as the vesicle pathway export." (PMID 41462686, 2025). "Although the concentrations of human exposure to CT vary, our data suggest that even at low concentrations of acute exposure to MC-LR, NOD, CYN, and BMAA change cell metabolic activities, increase inflammatory IL-6, SOD1, and TNFα gene expression, and cytotoxicity in neuroblastoma cells." (PMID 41424770, 2025). "To address whether Chem-036 could inhibit the neuronal cell death, which was induced by MT-SOD1 overexpression, we transfected human neuroblastoma cell (SK-N-MC and SK-N-SH) with expression vector constructs for each of SOD1 mutants." (PMID 34912047, 2021). "(2016), Nrf2 does not appear to be associated with SOD1 in human neuroblastoma SH-SY5Y cells that are exposed to H2O2." (PMID 33805942, 2021). "The drug rescued the cell death induced by mutant SOD1 in human neuroblastoma cell line." (PMID 34912047, 2021). "In particular, in in vitro studies, MIF chaperone activity inhibits the formation and toxicity of misfolded SOD1 amyloid aggregates, when overexpressed in neuroblastoma cell lines such as SH-SY5Y or mouse motor neuron-like hybrid cell line NSC-34 differentiable in motor neurons." (PMID 32344747, 2020). "Indeed, previous studies have suggested secretion of SOD1 from neuroblastoma SK-N-BE cells by microvesicular granules in ATP-dependent mechanisms and also from NSC-34 cells via exosomes." (PMID 31744522, 2019). "However, reduced rather than increased levels of activated Rac1 (Rac1GTP) were found in cell lysates of SH-SY5Y neuroblastoma cells overexpressing SOD1 mutants G93A and H80R." (PMID 30214670, 2018). "In addition, applying exogenously-aggregated mutant human SOD1 can induce subsequent aggregation of soluble transgenically-expressed mutant human SOD1 in mouse neuroblastoma cells." (PMID 25551548, 2014). "More importantly, amyloid-like fibrils of human apo-SOD1SH retain their seeding activity in the intracellular environment; transduction of those human SOD1 fibrils into cultured cells (mouse neuroblastoma, Neuro2a) has been shown to trigger the aggregation of stably-transfected human SOD1." (PMID 24672430, 2014). "Mutant SOD1 activated neuronal p38 in mouse spinal cord, neuroblastoma cells and squid axoplasm." (PMID 23776455, 2013). "Here we hypothesized that Ex-4 may provide neuroprotective activity in ALS, and hence characterized Ex-4 actions in both cell culture (NSC-19 neuroblastoma cells) and in vivo (SOD1 G93A mutant mice) models of ALS." (PMID 22384126, 2012). "We first tested whether PSA/NPEPPS overexpression is able to reduce the abundance of endogenous SOD1 in human neuroblastoma SH-SY5Y cells." (PMID 21548977, 2011).
neuroblastoma (continued). "Furthermore, overexpression of PDI in neuroblastoma cells decreased the levels of insoluble mutant SOD1, inhibited inclusion formation and decreased apoptotic cell death." (PMID 21603027, 2011). "In support of this possibility, we observe abnormal ER and numerous free ribosomes aggregated in the peri-nuclear region neuroblastoma cells expressing L84V SOD1 under ER stress condition and in spinal cord neurons in presymptomatic transgenic mice expressing L84V SOD1." (PMID 17925878, 2007). "Since the SOD1-positive inclusions of FALS patients are known to be eosinophilic, we performed hematoxylin-eosin (HE) and anti-SOD1 antibody staining to determine whether the aggregates induced in the neuroblastoma line were also eosinophilic." (PMID 17925878, 2007). "As expected, the SOD1 aggregates of the L84V SOD1-expressing neuroblastoma cells colocalized with caspase-4 (unpublished data), implying caspase-4 might contribute to cell death in our model system." (PMID 17925878, 2007). "The first demonstration of constitutive SOD1 secretion in many eukaryotic cells date back to many years ago when we, for the first time, showed the export of this protein in hepatocytes and fibroblasts, in neuroblastoma SK-N-BE cells and in thymus-derived epithelial cells." (PMID 37760050, 2023). "In the present study we show that CBR-470-1 activates the Nrf2 cascade in SH-SY5Y neuroblastoma cells, causing disassociation of the Keap1-Nrf2 complex, cytosol Nrf2 protein stabilization and nuclear translocation, followed by increased expression of Nrf2 pathway genes (HMOX1, NQO1 and SOD1)." (PMID 32649311, 2020). "In addition, in the attempt to evaluate the possible role carried out by SOD1 export, we recently demonstrated, in SK-N-BE neuroblastoma cell line, that this enzyme is able, through the involvement of muscarinic M1 receptor, to activate ERK1/2 and AKT in a dose and time-dependent manner." (PMID 27965593, 2016). "In addition, we demonstrated that in human neuroblastoma SK-N-BE cells, that show a greater sensitivity to glucose deprivation-induced cytotoxicity due to enhanced sensitivity to ROS, SOD1 export takes place in normal conditions and is increased following oxidative stress." (PMID 27965593, 2016). "However, considering that mutant SOD1 promotes apoptosis in oxidatively stressed neuroblastoma N2a cells by activating caspase-1 and increasing mature IL-1β secretion, we postulate that AAP-induced ROS production may be responsible for caspase-1 activation." (PMID 23166834, 2012). "CT exposure downregulates mitochondrial oxygen consumption rate in neuroblastoma SH-SY5Y cells, increases IL-6, SOD1, and TNFα expression, and enhances cell apoptosis." (PMID 41424770, 2025). "Previous in vitro studies have shown increased processing and nuclear translocation of ATF6 in N2a neuroblastoma cells overexpressing mutant SOD1G85R and an increase in SOD1 aggregates in the motoneuronal cell line NSC-34 following ATF6 knockdown." (PMID 37958767, 2023). "Honokiol has been shown to extend the lifespan of SOD1-G93A transgenic mice and improve their motor function and the viability of neuroblastoma/spinal cord NSC-34 hybrid cell lines and the morphology of mitochondria in SOD1-G93A cells." (PMID 37597078, 2023). "For example, inhibition of sodium nitroprusside-mediated NO release and increased production of transcripts coding for antioxidant enzymes (i.e., SOD1, GPx1 and CAT) have been reported upon melatonin treatment in neuroblastoma cells and HUVEC, respectively." (PMID 35883714, 2022). "Finally, SOD1 has also been reported to activate the muscarinic M1 receptor, thus inducing AKT and ERK phosphorylation in neuroblastoma SK-N-BE cells." (PMID 33805942, 2021). "Moreover, a reduced level of pyruvate was demonstrated in SOD1-G93A mice, as well as an increment in lactate in the same rodent model, in ALS homogenate from sporadic patients, and in G39-neuroblastoma spinal cord mutant cells." (PMID 32840822, 2020).
neuroblastoma (continued). "Finally, another study was performed to test in vitro if increased synthesis of MIF can prevent the accumulation of misfolded SOD1 and protect against its toxicity in the SH-SY5Y neuroblastoma cell line." (PMID 32344747, 2020). "Recently, we showed that SOD1 activates muscarinic M1 receptor inducing a phosphorylation of ERK1/2 and AKT in a dose and time dependent manner in neuroblastoma SK-N-BE cells; in fact, in presence of M1 antagonist pirenzepine, ERK1/2 and AKT phosphorylation, induced by SOD1, was strongly prevented." (PMID 27965593, 2016). "In this study, we examined alterations to cellular metabolism in a previously characterized motor neuronal ALS model system, the murine neuroblastoma × spinal cord (NSC-34) cell line, stably expressing human wild-type (wt) SOD1 (wtSOD1) or mutant G93A (G93ASOD1)." (PMID 25963727, 2016). "After exposure to pneumolysin, the capacity of G93A-SOD1 cells to control cytosolic Ca2+ by transport to the extracellular space or to intracellular storage sites was much lower than the capacity of neuroblastoma cells not transfected with mutant SOD1." (PMID 17997855, 2007). "Moreover, the incubation of SK-N-BE and the neuroblastoma–spinal motoneuron fusion NSC-34 cell line with mutant SOD1G93A significantly increased their intracellular Ca2+ concentration, as compared with wild-type SOD1 treatment." (PMID 37760050, 2023). "Similarly, the human neuroblastoma SH-SY5Y cell line has improved our understanding of not only SOD1 but also TDP-43-ALS pathology." (PMID 33921446, 2021). "The specificity of SOD1 surface binding to SK-N-BE membrane was strengthened by the fact that neither biotinylated human thyroglobulin nor human thyroperoxidase bound to the neuroblastoma cell membranes." (PMID 27965593, 2016). "To determine whether the MS785-MS27-reactive SOD1 species could exhibit toxic effects on cultured cells, we first investigated the proliferation of NSC-34 cells, a hybridoma with mouse spinal motor neurons and neuroblastoma cells, by measuring the metabolic activity using Cell Counting Kit-8." (PMID 38891791, 2024).
Cerebral ischemia (87 papers, 2009 to 2026). Restriction of arterial blood supply to the brain associated with insufficient oxygenation to support the metabolic requirements of the tissue. "NO-mediated S-nitrosylation of PDI may be involved in the formation of the SOD1-linked ubiquitinated-protein aggregates in cerebral ischemia/reperfusion injury." (PMID 23061969, 2012). "In a mouse model with a 50% reduction in SOD1 protein expression (Sod1+/−), the lower protein levels cause motor dysfunction and increase neurodegeneration and the sensitivity to other cellular stresses such as cerebral ischemia, leading to increased blood–brain barrier permeability." (PMID 39997953, 2025). "On the other hand, it has been studied that ischemic brain damage after transient global or focal cerebral ischemia is significantly attenuated in transgenic mice and rats overexpressing SOD1 or SOD2." (PMID 30696078, 2019). "Rg1 and Rb1 showed neuroprotective effects against cerebral ischemia by inducing SOD-1." (PMID 35268019, 2022).
metabolic syndrome (77 papers, 2011 to 2025). A cluster of metabolic risk factors for CARDIOVASCULAR DISEASES and TYPE 2 DIABETES MELLITUS. "In our investigated NonMetS-Nonfrail elderly patients, there was only an age and SOD-1 association, while in those with metabolic syndrome and/or frailty, SOD-1 was related to metabolic parameters." (PMID 39330521, 2024). "Furthermore, changes in SOD-1 activity have been linked to metabolic syndrome—the metabolic disorders characterized by obesity, hypertension, hyperglycemia, and dyslipidemia." (PMID 39330521, 2024). "One possible explanation for the discrepancies about the association between SOD1 activity and dyslipidemia could be genetic differences, as polymorphisms of SOD1 have been linked to differences in fat metabolism, for instance the −251 A > G SOD1 (rs2070424) polymorphism." (PMID 30487467, 2018). "The results of this study highlight the intricate relationship between superoxide dismutase 1, metabolic syndrome, and/or frailty syndrome in the elderly population." (PMID 39330521, 2024). "But, in those with metabolic syndrome who also were frail, the SOD-1 activity adversely corresponded with fasting glucose, suggesting the role of declining antioxidant capacity in the multiple syndromes." (PMID 39330521, 2024). "Downregulation of Gpx1, Pparα, and Sod1 transcripts by HFD exposure and mixed HFD and PM2.5 exposure affects this pathway, increasing the risk of dyslipidemia." (PMID 39766314, 2024). "SOD1−/− had less body weight than WT, even in ND; induction of metabolic syndrome in HFHSD resulted in attenuated weight gain, similar to WT in ND." (PMID 35883894, 2022). "As for SOD1, results are contradictory, as both reduced and increased activity of the enzyme has been found in patients with dyslipidemia." (PMID 30487467, 2018). "CO2 fosters SOD1 peroxidation, promoting the release of pro-inflammatory cytokines from activated macrophages leading to metabolic syndrome." (PMID 21599958, 2011). "OS in conditions like dyslipidemia often triggers cellular antioxidant responses, including the induction of protective buffer molecules and enzymes such as copper zinc superoxide dismutases (SOD1 and SOD3)." (PMID 39997704, 2025). "Comparing with our study, in frailty and/or metabolic syndrome elderly persons, the varying relationships between SOD-1 activity and different clinical parameters suggest that oxidative stress may influence various health outcomes." (PMID 39330521, 2024). "Thus, we have studied the activity of erythrocyte superoxide dismutase-1 (SOD-1) with regard to clinical conditions: metabolic syndrome and/or frailty syndrome diagnosed in elderly population." (PMID 39330521, 2024). "There is evidence to suggest that SOD-1 activity may be affected by metabolic syndrome in elderly individuals." (PMID 39330521, 2024). "Specifically, our results demonstrate that aging is accompanied by a significant decrease in the activity of the antioxidant enzyme superoxide dismutase-1 (SOD-1), with variations observed depending on the presence of metabolic syndrome and/or frailty syndrome." (PMID 39330521, 2024). "WT and SOD1−/− were fed on HFHSD to develop metabolic syndrome and compared with ND." (PMID 35883894, 2022). "Some studies have found that reduced SOD1 activity was associated with the presence of dyslipidemia, whereas others have not." (PMID 30487467, 2018). "Additionally, maintaining optimal activity of SOD-1 by staying active, adopting a nutritious diet, and incorporating other healthy habits may lower the chance of developing metabolic syndrome and slow down frailty." (PMID 39330521, 2024). "Several SNPs of SOD1 have been reported to correlate with metabolic disorders such as obesity, diabetes and its complications, cardiovascular disease, etc., but their associations with lipid profiles and dyslipidemia were absent." (PMID 32559230, 2020).
metabolic syndrome (continued). "Nevertheless, all the major antioxidant proteins, including catalase and SOD1, were found to be decreased in the adipocytes of OVX rats with metabolic syndrome and were restored back with E2 supplementation." (PMID 31100969, 2019). "Metabolic syndrome was induced by feeding on HFHSD for 24 weeks, and as in previous reports, skeletal muscle from HFHSD-fed mice showed red fluorescence in DHE staining and even stronger fluorescence in SOD1−/−, reflecting cytosolic O2·−." (PMID 35883894, 2022).
Stroke (72 papers, 2011 to 2026). Sudden impairment of blood flow to a part of the brain due to occlusion or rupture of an artery to the brain. "Overexpression of both SOD1 (Cu/Zn-SOD, cytosolic) and SOD2 have been shown to reduce stroke-related deficits, while deficiencies in these enzymes have been associated with larger infarct volumes." (PMID 30037107, 2018). "Conversely, SOD1 displayed a uniform reduction in the infarcted tissue of stroke patients when sampled from three different locations of the brain." (PMID 28800743, 2017). "Approaches to overexpress SOD1 using transgenic mice and rats demonstrated reduced apoptosis in transient focal ischaemia stroke models." (PMID 26785066, 2014). "On the other hand, SOD-1 is protective for HI conditions, such as stroke." (PMID 35250486, 2022). "Also, transplantation of NSCs overexpressing Cu/Zn-superoxide dismutase (SOD1) into peri-infarct mouse cortex 2d post-stroke enhanced angiogenesis, which is potentially mediated by upregulation of VEGF." (PMID 34299322, 2021). "Also, intracranial administration of SOD1-overexpressing NSCs 2d post-stroke improved behavioral performance as assessed over 28d by mNSS scoring and the rotarod test." (PMID 34299322, 2021). "However, there were very few NeuN positive cells less than 20 μm in lamina IX in either WT or G93A SOD1 mice, and thus pyknotic motor neurons would have to have lost their NeuN staining (which has been reported in neurons in an experimental stroke model)." (PMID 21767396, 2011). "Proteomic profiling of brain‐ and biofluid‐derived EVs has uncovered specific biomarkers and signaling pathways, ranging from tau and α‐synuclein in AD and PD to mutant SOD1 in ALS and complement activation in stroke and TBI." (PMID 41532955, 2026). "The regulatory effects of the core genes of the ALS pathway (SOD1, FUS, TARDBP) on ROS metabolism and inflammatory responses are common pathological drivers of Osteoporosis and stroke." (PMID 41379792, 2025). "Of the three SOD enzyme isoforms, SOD1 has been studied most in relation to experimental models of stroke." (PMID 26785066, 2014). "However, in these plants, the number of candidate anti-stroke compounds for each targets dramatically reaches a maximum of 134 (target NOS3) and a minimum of 62 (target SOD1)." (PMID 28117389, 2017).